CRP (C-reactive protein)
Diseases named in the same sentence as CRP in open-access papers (continued):
Sharing a sentence is not in itself a finding about the gene and the disease.
acute cholecystitis (31 papers, 2012 to 2026). "Diagnostic symptoms of acute cholecystitis include upper-quadrant pain, positive Murphy’s sign, elevated c-reactive protein (CRP) and leukocytes, and fever." (PMID 40766096, 2025). "Increasing age and rising CRP showed significant association with intra-operative diagnosis of complicated acute cholecystitis." (PMID 33796428, 2021). "Teckchandani and co-investigators observed that a raised CRP on admission in cases of acute cholecystitis was associated with a higher emergency laparoscopic converted to an open cholecystectomy procedure." (PMID 31281756, 2019). "Portinari and co-workers observed that a high CRP was associated with severe acute cholecystitis, and these patients may benefit from an emergency cholecystectomy." (PMID 31281756, 2019). "This study developed and validated a clinically practical scoring system based on key radiographic and laboratory parameters—gangrenous change, GB wall HU value, WBC, and CRP—for the early identification of complicated acute cholecystitis." (PMID 40722527, 2025). "The WBC count and CRP at discharge were significantly higher in patients with moderate acute cholecystitis." (PMID 39860547, 2025). "The decision tree analysis identified C-reactive protein (CRP) level, the presence of gangrene, and the gallbladder (GB) wall’s Hounsfield unit (HU) value as key predictors of complicated acute cholecystitis (ACC)." (PMID 40722527, 2025). "Previously established literature demonstrates a correlation between peripheral blood CRP concentration and the severity of acute cholecystitis, with some studies suggesting its utility as a reliable predictor of inflammatory burden." (PMID 38523838, 2024). "NICE refer to CRP in confirmation of acute cholecystitis, while the Tokyo Guidelines for diagnosis refer to both CRP and white cell count (WCC) and differentiate grades with WCC." (PMID 35334564, 2022). "CRP, NLR and age were found to be independent factors associated with severity of acute cholecystitis and able to predict CAC." (PMID 33796428, 2021). "Ultrasound findings, which indicate acute cholecystitis, alongside the elevation in CRP levels (3 mg/dl or higher) have a 97% sensitivity, 76% specificity, and 95% positive-predictive value in the diagnosis of acute cholecystitis." (PMID 32399305, 2020). "The fewer abdominal symptoms in the elderly, the lesser responsiveness of WBC and CRP levels with aging, and the higher rate of severe and or gangrenous acute cholecystitis in the elderly should be explored further." (PMID 30867674, 2019). "Laboratories were elevated with WBC count of 14 and CRP 48, and both surgeon and radiologist noted a thickened wall of the gallbladder, suggesting acute cholecystitis." (PMID 29882098, 2018). "Neutrophil-to-lymphocyte ratio (NLR) and C-reactive protein (CRP) are inflammatory biomarkers that could predict the diagnosis and complications of acute cholecystitis." (PMID 42122065, 2026). "Fat stranding, C-reactive protein levels, gamma-glutamyltransferase levels, and age are predictors of length of stays in addition to the 2018 Tokyo Guidelines grade among patients with acute cholecystitis." (PMID 39407793, 2024). "CRP, NLR and age were independent factors associated with the severity of acute cholecystitis." (PMID 33796428, 2021). "The 2018 Tokyo guidelines (TG18) provide parameters for the diagnosis of acute cholecystitis (physical examination, C-reactive protein [CRP], white blood cell [WBC] count and radiology) as well as risk stratification parameters including a raised WBC count of >18x109/L." (PMID 33796428, 2021). "Thus, while NLR may be useful in diagnosing acute cholecystitis, CRP could be more effective in assessing disease severity." (PMID 42122065, 2026). "In addition, CRP has also shown promise as a predictor of severity in acute cholecystitis." (PMID 33796428, 2021).
acute cholecystitis (continued). "Upon admission, inflammatory marker levels, such as the white blood cell count (WBC) and C-reactive protein (CRP), were elevated in both groups, with higher values observed in patients with moderate acute cholecystitis." (PMID 39860547, 2025). "In case 7, WBC and CRP did not increase significantly after the onset of acute cholecystitis, but there was a significant increase in the level of hepatobiliary enzyme." (PMID 37875814, 2023). "Acute cholecystitis (AC) defined by right upper quadrant pain, presence of Murphy’s sign, fever, elevated white blood cell count (WBC), and C-reactive protein (CRP) is one of the most common gastrointestinal diseases that require hospitalization and surgical treatment." (PMID 35308770, 2022). "We aim to evaluate whether the use of pre-operative CRP and neutrophil-lymphocyte ratio (NLR) as surrogate markers could serve to differentiate between uncomplicated acute cholecystitis (UAC) and CAC." (PMID 33796428, 2021). "Similarly, laboratory tests, including inflammatory markers (white blood cell count, C-reactive protein) and liver function tests (bilirubin, transaminases, alkaline phosphatase), are not specific for the diagnosis of acute cholecystitis in pregnant women." (PMID 39246860, 2024). "Our study aimed to investigate patients displaying no signs of systemic inflammation (fever, normal ranged CRP and WBC) with radiologic evidence of acute cholecystitis based on the guidelines provided above." (PMID 33173625, 2020).
cholangitis (31 papers, 2011 to 2025). An acute or chronic inflammatory process affecting the biliary tract. "This is supported by our data showing that prohepcidin levels in the bile are elevated in patients with PSC-associated cholangitis, in whom they tightly correlate with serum CRP and bilirubin levels, the two important parameters of disease severity." (PMID 21283681, 2011). "Cholangitis severity, CRP, and procalcitonin levels were significantly higher in the ERCP within 72 h group (p < 0.001)." (PMID 40474397, 2025). "Tumors located at the head or uncinate process often invade the bile duct or duodenum, resulting in biliary obstruction and cholangitis, which can elevate serum CRP levels." (PMID 34945079, 2021). "In patients with a previous inflammatory condition such as cholangitis or other infections, we observed that TNFα, CRP and leukocytes were elevated prior to ERCP, but remained stable 4 hours after the procedure." (PMID 27642079, 2016). "Second, there was clear evidence of infection, including C-reactive protein, cholangitis, and positive blood culture, in patients with black pigment stones." (PMID 27785202, 2012). "In PSC-cholangitis subjects, bile prohepcidin levels positively correlated with C-reactive protein and bilirubin levels (r = 0.48 and r = 0.71, respectively)." (PMID 21283681, 2011). "Notably, CRP, an inflammatory marker primarily produced by hepatocytes, was elevated in the stool of individuals with recurrent cholangitis." (PMID 40585902, 2025). "Notably, C-reactive protein levels were elevated, whereas sodium/hydrogen exchanger 3 levels were decreased in the group with repeated cholangitis." (PMID 40585902, 2025). "Laboratory elements defining cholangitis included increased levels of WBCs 95.1% (59/62), CRP 90.3% (56/62), PCT 54.8% (34/62), bilirubin 96.7% (60/62), gamma-glutamyl transferase (GGT) 90.3% (56/62), transaminases 85.4% (53/62), and positive blood cultures 79% (49/62)." (PMID 35159946, 2022). "Patients enrolled in the present study underwent blood sampling before the biliary drainage, and we can infer that the elevated serum CRP level might have resulted from cholangitis." (PMID 34945079, 2021). "Moreover, in PSC patient with cholangitis, prohepcidin levels correlated with CRP (r = 0.48, p = 0.03) and bilirubin serum levels (r = 0.71, p = 0.0002) thereby suggesting that prohepcidin levels in the bile reflect the extent of biliary infection." (PMID 21283681, 2011). "Additionally, CRP levels were elevated in the stools of patients with recurrent cholangitis." (PMID 40585902, 2025). "Notably, CRP levels were elevated in the stools of patients with repeated cholangitis (Group B)." (PMID 40585902, 2025). "However, the severe cholangitis group had significantly higher body temperature, WBC count, CRP, ALT, AST, γ-GGT, and DBIL." (PMID 37678274, 2023). "In addition, in patients with severe cholangitis, MEPM+IVIG significantly decreased WBC, EUC, CRP, ALT, AST, γ-GGT, and DBIL compared to MEPM (all P<0.05)." (PMID 37678274, 2023). "In another study, fever of 37.8 °C and above, WBC > 9000/μL or <4000/μL, and CRP increase within seven days after ERCP, were regarded as indices of post-ERCP cholangitis, and post-ERCP cholangitis rates were calculated as 40.7% after plastic stent placement in patients with cholangiocarcinoma." (PMID 36161594, 2022). "Over 14% of the PDAC patients had cholangitis and showed only slightly higher values of CRP (p-value = 0.064), which were not significant." (PMID 34677378, 2021). "Multivariate logistic regression analysis identified the following statistically significant predictive factors for the immediate development of cholangitis after PTBD: history of cholangitis, recent biliary drainage (≤6 months), elevated C-reactive protein and low serum albumin concentration." (PMID 25148939, 2014). "Furthermore, the GBC patients had elevated levels of C-reactive protein (CRP) compared to the controls, which might be due to high levels of cholangitis." (PMID 40941022, 2025).
cholangitis (continued). "Although a diagnosis of cholangitis was not recorded in this study cohort, the average CRP and total bilirubin levels in the stage 1 patients of >77 mg/L and >324 μmol/L, respectively, may be indicative of cholangitis." (PMID 35020761, 2022). "Interestingly, suspected biliary strictures after OLT or choledocholithiasis, as well as markedly elevated CRP levels were significantly more common in the cholangitis than in the non-cholangitis group, but after multivariate analysis adjustment, this difference did no longer reach significance." (PMID 37013522, 2023).
hepatitis B (31 papers, 2008 to 2026). "Abnormal expression of TNF-α, CRP and IL-6 inflammatory markers can promote liver inflammation, fibrosis and damage and aggravate liver function damage and disease severity of hepatitis B complicated with alcoholic cirrhosis." (PMID 41281287, 2025). "The prediction models incorporated zonulin, LPS, LBP, C-reactive protein, age, and history of hepatitis B for AKI, and zonulin, LPS, LBP, total bilirubin, and Child–Pugh score for HRS–AKI." (PMID 37567912, 2023). "These include CRP and viral markers of all admitted patients for Hepatitis B, C and HIV." (PMID 28286827, 2017). "In addition, CRP > 100 mg/L can be a promising marker of severe bacterial peritonitis and poor outcomes, and it can be markedly elevated in spontaneous bacterial peritonitis correlated with chronic severe hepatitis B." (PMID 37873776, 2023). "Laboratory investigations, including complete blood count with differential, liver and renal function tests, hepatitis B serology, hepatitis C antibody, HIV p24 antigen test, hemoglobin A1c, erythrocyte sedimentation rate (ESR), and C-reactive protein (CRP), were all within normal limits." (PMID 40831831, 2025). "Nevertheless, probiotic intake in general was associated with lower CRP concentrations in all patients and with lower AST activity in patients without hepatitis B or C virus infection, which points towards its mild protective effect on the allograft." (PMID 33204004, 2020). "However, the average C-reactive protein in the hepatitis B virus infection group was significantly higher than the non-carriers (P < 0.01)." (PMID 30971239, 2019).
Hypocalcemia (31 papers, 2009 to 2026). An abnormally decreased calcium concentration in the blood. "Headache prevailed and hypoxemia, hypocalcemia, elevated ferritin, and C-reactive protein were associated with NM." (PMID 35626923, 2022). "Under normal circumstances, hypocalcaemia (low blood calcium levels) may be associated with elevated C-reactive protein levels." (PMID 41602421, 2026). "Hypoxemia, hypocalcemia, elevated ferritin, and C-reactive protein were associated with NMs." (PMID 35626923, 2022). "This occurs because hypocalcaemia can stimulate the release of certain cytokines, thereby promoting C-reactive protein production." (PMID 41602421, 2026). "Biochemical results showed that most patients were anemic with high C-reactive protein levels, hypocalcemia, hyperphosphatemia, elevated parathyroid hormone and decreased 25-hydroxy vitamin D. At the end of one year, 60 patients died (14.1%)." (PMID 28045952, 2017). "Laboratory studies done for our case included CBC, chemistry, bone panel, liver profile, lactate dehydrogenase (LDH), C-reactive protein, and coagulation profile; all were unremarkable, aside from a hypocalcemia of 1.99 mmol/L, an elevated LDH of 537 U/L, and a slightly elevated coagulation profile." (PMID 39588414, 2024). "Local acidosis, mild hypocalcaemia and high CRP level are characteristic of local inflammation." (PMID 19180241, 2009). "Compared to persistently normocalcemic patients, those with severe hypocalcemia were more often diabetic, overweight, had cardiovascular disease, shorter dialysis vintage, used a catheter dialysis access, had fewer active vitamin-D sterols, and exhibited higher CRP and iPTH and lower calcium levels." (PMID 31848883, 2020). "All TB patients had elevated pre-therapy levels of CRP and reduced HDL: 88.9% presented hypocalcemia and 47.2% showed elevated ALP and GGT." (PMID 37510958, 2023). "In conclusion, TB patients showed elevated pre-therapy levels of CRP, low levels of HDL, and hypocalcemia." (PMID 37510958, 2023). "Before starting the treatment, these patients showed elevated levels of CRP, low levels of HDL, and hypocalcemia." (PMID 37510958, 2023). "The C-reactive protein (CRP) was increased at 197mg/l, the sedimentation rate (sed-rate) was at 111, the Lactate Dehydrogenase test (LDH) was at 342 u/l and a hypocalcaemia." (PMID 29138655, 2017). "Similarly, risk factors associated with severe hypocalcemia (catheter access, net ultrafiltration, CRP levels, and no paricalcitol use) were of uncertain clinical relevance as we had limited number of severe hypocalcaemia episodes to come to clear conclusions." (PMID 31848883, 2020). "Phosphorus showed a slight within-reference increase and C-reactive protein (CRP) rose markedly, with no concurrent hyperkalemia or hypocalcemia." (PMID 41150122, 2025).
intracerebral hemorrhage (31 papers, 2013 to 2026). A cerebrovascular disorder characterized by bleeding into one or both cerebral hemispheres including the basal ganglia and the cerebral cortex. "Monomeric C-reactive protein (mCRP), derived from the dissociation of the native pentameric CRP (pCRP), has been implicated in the pathophysiology of various neurological conditions, particularly intracerebral hemorrhage (ICH) and neurodegenerative diseases." (PMID 40649973, 2025). "In contrast, no conclusive relationship has been established between serum CRP levels and intracerebral hemorrhage risk." (PMID 40649973, 2025). "C-reactive protein, an important inflammatory marker, is associated with intracerebral hemorrhage outcomes." (PMID 36138906, 2022). "In particular, there is limited evidence on the associations of systemic inflammation, including CRP and fibrinogen, with risk of intracerebral hemorrhage (ICH)." (PMID 32221345, 2020). "Elevation of CRP during the acute-phase response in intracerebral hemorrhage (ICH) is also associated with the outcomes such as death and vascular complications." (PMID 30254628, 2018). "Higher levels of CRP are significantly associated with 30-day death after sICH and an independent predictor of poor outcome in intracerebral haemorrhage." (PMID 26264492, 2015). "CRP is increased in response to acute inflammation, leads to cell apoptosis, and has been shown in previous studies to be a predictor of mortality and associated with worse outcomes after intracerebral hemorrhage." (PMID 33585095, 2021). "Notably, over recent decades CRP has been the focus of an intense investigation to explore its role in the setting of intracerebral hemorrhage (ICH) and currently is proposed as a risk assessment tool and prognostic marker." (PMID 30254628, 2018). "Although systemic CRP rises early after intracerebral hemorrhage as part of the body’s acute-phase defense, mCRP follows a distinct timeline, appearing only later in brain regions surrounding the hematoma." (PMID 40649973, 2025). "We conducted a retrospective chart review of patients with spontaneous intracerebral hemorrhage with TNFα, CRP, VEGF, Hcy levels drawn on admission." (PMID 33585095, 2021). "The aim of the present study was to investigate the relationship between PCT levels and both fever etiology and CRP levels among critically ill patients with intracerebral hemorrhage." (PMID 31691767, 2019). "Increasing levels of serum CRP have been described to indicate growing intracerebral hematomas and mortality in patients with intracerebral hemorrhage, and to predict poor neurofunctional outcome and death in patients with acute ischemic stroke." (PMID 26450065, 2015). "Recent work demonstrated that the level of inflammatory marker CRP was elevated in patients with intracerebral hemorrhage in alcohol users." (PMID 24044608, 2013). "The C-reactive protein levels showed an acute inflammatory response, which ultimately led to multiple lethal symptoms such as septic multi-organ failure, COVID-19 pneumonia, hypoxia, septic cardiovascular failure, and intracerebral hemorrhage, among others." (PMID 38674011, 2024). "Future studies directed at lowering CRP, TNFα, and Hcy and/or increasing VEGF in intracerebral hemorrhage patients are needed and may be beneficial." (PMID 33585095, 2021). "This current study looks to expand on our prior results and will look at the relationship between tumor necrosis factor alpha (TNFα), C-reactive protein (CRP), VEGF, Homocysteine (Hcy), and CRP to albumin ratio (CAR) in predicting outcomes and severity in spontaneous intracerebral hemorrhage." (PMID 33585095, 2021).